SAP130 (Sin3A associated protein 130)
Description:
Acts as a transcriptional repressor. May function in the assembly and/or enzymatic activity of the mSin3A corepressor complex or in mediating interactions between the complex and other regulatory complexes.
Synonyms: FLJ12761
Tractability: PROTAC: UniProt records ubiquitination sites on it; ubiquitination databases record sites on it; its protein half-life has been measured.
Gene: Protein-coding gene on chromosome 2 (127,941,217 to 128,028,124, reverse strand). Ensembl gene ENSG00000136715.
Subcellular location: Nucleus
Subcellular location (Human Protein Atlas): Nuclear speckles
Pathways (Reactome):
Chromatin organization: HATs acetylate histones
Gene expression (Transcription): NoRC negatively regulates rRNA expression
Gene Ontology:
Biological process: negative regulation of transcription by RNA polymerase II; negative regulation of cell migration; negative regulation of stem cell population maintenance; negative regulation of transforming growth factor beta receptor signaling pathway; positive regulation of stem cell population maintenance; regulation of DNA-templated transcription
Cellular component: nuclear speck; nucleus; Sin3-type complex
Genetic constraint (gnomAD): Loss-of-function variants: 13 observed, 84.96 expected, observed/expected ratio (o/e) 0.15, 90% interval 0.099 to 0.24. The upper end of that interval is the gene's LOEUF score, 0.24, which puts it in group 1 of 6, group 1 being the genes least tolerant of losing a copy. Missense variants: 950 observed, 1,330 expected, observed/expected ratio (o/e) 0.71, 90% interval 0.68 to 0.75. Synonymous variants: 461 observed, 493.86 expected, observed/expected ratio (o/e) 0.93, 90% interval 0.86 to 1.01.
Homologues: Orthologues: chimpanzee SAP130 (100% identical), macaque SAP130 (99% identical), rabbit SAP130 (98% identical), pig SAP130 (98% identical), dog SAP130 (97% identical), mouse Sap130 (94% identical), rat Sap130 (94% identical), guinea pig SAP130 (85% identical), tropical clawed frog sap130 (71% identical), zebrafish sap130b (60% identical), zebrafish sap130a (59% identical), Drosophila melanogaster Sap130 (24% identical).
Diseases named in the same sentence as SAP130 in open-access papers:
SAP130 is named in the same sentence as 28 diseases in open-access papers, as found by Europe PMC text mining. Sharing a sentence is not in itself a finding about the gene and the disease. The quoted sentences say what the papers report.
pancreatic ductal adenocarcinoma (5 papers, 2017 to 2023). An infiltrating adenocarcinoma that arises from the epithelial cells of the pancreas. "Importantly, Mincle activation through recognizing SAP130 contributed to the ethanol-induced liver injury, traumatic brain injury, and pancreatic ductal adenocarcinoma progression." (PMID 34556635, 2021). "Similarly, high cytoplasmic SAP130 expression in human pancreatic ductal adenocarcinoma (PDA) was observed which correlated with high RIP1/RIP3 expression, the key regulators of necroptosis." (PMID 34556635, 2021). "In pancreatic ductal adenocarcinoma (PDA), the necroptotic pathway was found to promote oncogenesis through releasing the chemokine (C-X-C motif) ligand 1 (CXCL1) and 130 kDa Sin3-associated polypeptide (SAP-130), which induce immune-suppression in the tumor microenvironment." (PMID 31922095, 2019).
acute kidney injury (3 papers, 2021 to 2025). Sudden and sustained deterioration of the kidney function characterized by decreased glomerular filtration rate, increased serum creatinine or oliguria. "It has been reported that SAP130 released by damaged or dead tubular cells increases the expression of Mincle and its downstream molecules to promote macrophage activation, which, in turn, aggravates tubular epithelial cell death in acute kidney injury animal models." (PMID 40792209, 2025).
autoimmune hepatitis (2 papers, 2017 to 2025). Hepatitis caused by autoantibodies. "Similarly, the upregulation of Mincle and SAP130 in the liver was observed in both mice and humans with autoimmune hepatitis, which was attenuated by Mincle blockage or deletion but aggravated by Mincle ligation." (PMID 40792209, 2025).
hypoplastic left heart syndrome (2 papers, 2017 to 2018). Hypoplastic left heart syndrome (HLHS) refers to the abnormal development of the left-sided cardiac structures, resulting in obstruction to blood flow from the left ventricular outflow tract. "Forward genetics in mice was used recently to identify an interaction between two genes, Sap130 and Pcdha9, in causing hypoplastic left heart syndrome (HLHS)." (PMID 30355621, 2018).
ischemic stroke (2 papers, 2021 to 2025). A stroke disorder caused by obstruction of blood flow to the brain, due to thrombotic (local blood clot formation) or embolic (due to a blood clot or other material traveling from another site) event. "Mincle can induce proinflammatory responses in ischemic stroke model once binding Sin3A associated protein 130 (SAP130), a small ribonucleoprotein released by dying cells." (PMID 34154653, 2021). "Activation of the Mincle signaling pathway through its ligands, such as SAP130 or properdin, facilitated the progression of ischemic stroke, and pharmacological inhibition or knockdown of Mincle signaling can mitigate damage." (PMID 40792209, 2025). "In the central nervous system, it has been found that the SAP130/Mincle axis is involved in promoting neuroinflammation in various brain injury rodent models, including ischemic stroke, traumatic brain injury, and subarachnoid hemorrhage." (PMID 40792209, 2025).
multiple sclerosis (2 papers, 2021 to 2025). A progressive autoimmune disorder affecting the central nervous system resulting in demyelination. "Consistently, the SAP130/Mincle pathway was activated in multiple sclerosis, and Mincle silencing or SAP130 neutralization has protective effects by suppressing neuroinflammation." (PMID 40792209, 2025). "Blockade of endogenous ligand SAP130 was also efficient to control the development of multiple sclerosis." (PMID 34556635, 2021).
pancreatic cancer (2 papers, 2024 to 2025). "And pancreatic cancer model showed that necroptosis induced immune tolerance TME through the CXCL1-CXCR2 and SAP130-Mincle signaling axis." (PMID 41249133, 2025). "Necroptotic pancreatic cancer cells induce peri-necroptotic immune suppression and invasion through CXCL1, CXCL5 and SAP130-Mincle signalling." (PMID 38926796, 2024).
acute tubule necrosis (1 paper, 2021). "Firstly, we found that cytoplasmic SAP130 was increased in injured TECs accompanied with Mincle expression in AKI mice as well as in patients with acute tubule necrosis." (PMID 34556635, 2021). "Our data demonstrated that the release of cytoplasmic SAP130 from injured TECs was increased in both the AKI mice model and clinic patients with acute tubule necrosis (ATN)." (PMID 34556635, 2021).
Cognitive impairment (1 paper, 2025). Abnormal cognition is characterized by deficits in thinking, reasoning, or remembering. "Interference with SAP130 or the downstream Mincle pathway may represent a potential therapeutic strategy to ameliorate sevoflurane-induced neurotoxicity or even cognitive impairment." (PMID 40792209, 2025).
dysplasia (1 paper, 2023). A usually neoplastic transformation of the cell, associated with altered architectural tissue patterns. "In pigs a CRISPR generated SAP130 allele caused embryonic lethality and tricuspid dysplasia and atresia, indicating SAP130 involvement in cardiac development in higher vertebrates." (PMID 37711853, 2023).
Infertility (1 paper, 2025). "The expression of key circRNAs (hsa-SAP130_0002, hsa-TRPC1_0001, hsa-FBRS_0001, hsa-ACACA_0025, hsa-UTRN_0042, and hsa-ZNF532_0023) was then validated by qPCR, and their diagnostic accuracy for infertility was confirmed through receiver operating characteristic curve analysis." (PMID 40391511, 2025).
tumor (12 papers, 2015 to 2024). "Interaction of TAMs and tumor cells via ligation of Mincle and Sin3A-associated protein 130 (SAP130) polarizes TAMs to immune suppressive M2 phenotype, resulting in adaptive immune suppression and tumor progression." (PMID 36230914, 2022). "For instance, necroptosis-mediated dying tumor cells induce the C-X-C motif chemokine ligand 1 (CXCL1) and sin3A-associated protein 130 (SAP130) release to aggravate inhibitory TIME." (PMID 36466844, 2022). "Various DAMPs are produced by tumor cells undergoing immunological cell death [e.g., calreticulin, HighMobility Group Box 1 protein (HMGB1) or Sin3A Associated Protein 130 (SAP130)]." (PMID 30800125, 2019). "Mechanistically, this was linked to an increased RIPK1/RIPK3-dependent protein product of PDA cells (SAP130), which promoted cellular immune suppression by tumour infiltrating macrophages expressing the protein receptor (Mincle) that were themselves recruited in a CXCL1-dependent manner." (PMID 31416294, 2019). "Given that FAF1 has been implicated as a tumor-suppressor and we demonstrated that FAF1 inhibits SAP130-mediated transcriptional function, stability and cell proliferation-promoting ability, it is possible that FAF1 would attenuate any oncogenic potential of SAP130." (PMID 38172660, 2024). "It will therefore be of interest to further clarify whether SAP130 has tumor-promoting potential." (PMID 38172660, 2024). "In HER2− tumours, baseline expression of 48 genes associated with poor antiproliferative response (p < 0.005) including PERP and YWHAQ, the two most significant, and the transcription co-regulators (SAP130, HDAC4, and NCOA7) which were among the top 16 most significant." (PMID 31892336, 2019). "Mincle, SAP130 cognate receptor which can promote sterile inflammation by ligating SAP130 104, 105, was upregulated in PDA tumor-infiltrating myeloid cells." (PMID 34093836, 2021). "The SENP1 expression level positively correlated with the expression levels of UBN1, SP3, SAP130, NUP98, NUP153 in 32 tumor types." (PMID 34276383, 2021).
cancer (2 papers, 2021 to 2024). A tumor composed of atypical neoplastic, often pleomorphic cells that invade other tissues. "SAP130/Mincle axis participates in the pathogenesis of necroinflammation during tissue damages, cancer progression, or ischemia/reperfusion." (PMID 34556635, 2021). "To further study the relationship between expression of SAP130 and FAF1 in clinical samples, we analyzed the cancer datasets via cBioPortal database." (PMID 38172660, 2024). "Notably, analysis of the cancer datasets via cBioPortal database revealed that the mRNA level of SAP130 was negative correlated with FAF1 mRNA level in several types of cancers." (PMID 38172660, 2024).
SAP130 also shares sentences with these, for which no sentence is quoted: subarachnoid hemorrhage (2 papers); breast carcinoma (1); cognitive disorder (1); colitis (1); colorectal adenocarcinoma (1); diffuse large B-cell lymphoma (1); heart disease (1); hydronephrosis (1); Hydroureter (1); ischemia (1); prostate adenocarcinoma (1); Sepsis (1); thyroid carcinoma (1); Ureteral obstruction (1); ventricular septal defect (1).